RNU6-298P (RNA, U6 small nuclear 298, pseudogene)
Gene: Small nuclear RNA gene on chromosome 17 (30,861,843 to 30,861,938, forward strand). Ensembl gene ENSG00000212190.
Homologues: Orthologues: chimpanzee U6 (100% identical), macaque U6 (95% identical), rat LOC120094561 (83% identical). Paralogues in human: RNU6-1077P (88% identical), RNU6-1152P (84% identical), RNU6-429P (84% identical), RNU6-106P (83% identical), RNU6-589P (83% identical), RNU6-869P (83% identical), RNU6-1031P (82% identical), RNU6-1084P (82% identical), RNU6-116P (82% identical), RNU6-12P (82% identical), RNU6-13P (82% identical), RNU6-16P (82% identical), and 1287 more.